DNAJC5 (DnaJ heat shock protein family (Hsp40) member C5)
Description:
Acts as a general chaperone in regulated exocytosis (By similarity). Acts as a co-chaperone for the SNARE protein SNAP-25 (By similarity). Involved in the calcium-mediated control of a late stage of exocytosis (By similarity). May have an important role in presynaptic function. May be involved in calcium-dependent neurotransmitter release at nerve endings (By similarity).
Synonyms: CSP; CLN4; FLJ00118; FLJ13070; DNAJC5A; CLN4B; mir-941-2; mir-941-3; mir-941-4; mir-941-5
Tractability: Antibody: UniProt places it where antibodies can reach, with high confidence; its Gene Ontology location is reachable by antibodies, with high confidence. PROTAC: ubiquitination databases record sites on it; its protein half-life has been measured.
Gene: Protein-coding gene on chromosome 20 (63,894,641 to 63,936,031, forward strand). Ensembl gene ENSG00000101152.
Subcellular location: Cytoplasm, cytosol; Membrane; Cytoplasmic vesicle, secretory vesicle, chromaffin granule membrane; Melanosome; Cell membrane
Subcellular location (Human Protein Atlas): Vesicles; End piece; Golgi apparatus; Perinuclear theca; Principal piece
Pathways (Reactome):
Immune System: Neutrophil degranulation
Neuronal System: GABA synthesis, release, reuptake and degradation
Sensory Perception: Sensory processing of sound by inner hair cells of the cochlea
Gene Ontology:
Molecular function: protein binding; ATP-dependent protein binding
Biological process: exocytosis; protein folding; regulated exocytosis; regulation of synaptic vesicle cycle; synaptic vesicle exocytosis
Cellular component: lysosomal membrane; melanosome; membrane; mitochondrion; plasma membrane; azurophil granule membrane; clathrin-sculpted gamma-aminobutyric acid transport vesicle membrane; cytosol; presynapse; specific granule membrane; chromaffin granule membrane; cytoplasm; neuromuscular junction; synaptic vesicle; synaptic vesicle membrane
Genetic constraint (gnomAD): Loss-of-function variants: 1 observed, 23.11 expected, observed/expected ratio (o/e) 0.0433, 90% interval 0.014 to 0.2. The upper end of that interval is the gene's LOEUF score, 0.2, which puts it in group 1 of 6, group 1 being the genes least tolerant of losing a copy. Missense variants: 180 observed, 258.8 expected, observed/expected ratio (o/e) 0.7, 90% interval 0.62 to 0.79. Synonymous variants: 136 observed, 118.78 expected, observed/expected ratio (o/e) 1.14, 90% interval 1 to 1.32.
Gene-disease validity (ClinGen):
ClinGen rates the evidence that DNAJC5 causes each of these diseases.
adult neuronal ceroid lipofuscinosis (autosomal dominant): Moderate.
Homologues: Orthologues: chimpanzee DNAJC5 (100% identical), guinea pig DNAJC5 (100% identical), macaque DNAJC5 (100% identical), mouse Dnajc5 (99% identical), rat Dnajc5 (99% identical), dog DNAJC5 (94% identical), pig DNAJC5 (85% identical), zebrafish dnajc5aa (84% identical), tropical clawed frog dnajc5 (82% identical), zebrafish dnajc5ab (77% identical), Drosophila melanogaster l(3)80Fg (27% identical), Caenorhabditis elegans dnj-8 (25% identical), and 7 more. Paralogues in human: DNAJC5B (67% identical), DNAJC5G (43% identical), DNAJC13 (36% identical), DNAJC10 (33% identical), DNAJC21 (33% identical), DNAJC16 (31% identical), DNAJC18 (31% identical), DNAJC11 (31% identical), DNAJC7 (26% identical), DNAJC2 (25% identical), DNAJC14 (24% identical), DNAJC1 (23% identical), and 8 more.
Diseases named in the same sentence as DNAJC5 in open-access papers:
DNAJC5 is named in the same sentence as 47 diseases in open-access papers, as found by Europe PMC text mining. Sharing a sentence is not in itself a finding about the gene and the disease. The quoted sentences say what the papers report.
neuronal ceroid lipofuscinosis (18 papers, 2011 to 2025). "Mutations in DNAJC5/CSPα are associated with adult neuronal ceroid lipofuscinosis (ANCL), a dominant-inherited neurodegenerative disease featuring lysosome-derived autofluorescent storage materials (AFSMs) termed lipofuscin." (PMID 35506243, 2023). "Adult-onset neuronal ceroid lipofuscinosis is usually due to autosomal dominant mutations in the DNAJC5 gene (CLN4), which encodes a co-chaperone cysteine string protein-α." (PMID 37998376, 2023). "DNAJC5 mutations preventing vesicle trafficking (previously identified in adult neuronal ceroid lipofuscinosis, a human congenital disease) inhibit ExoU-dependent cell lysis." (PMID 34188051, 2021). "Autosomal dominant mutations in the DNAJC5 gene, encoding cysteine string protein α, cause a hereditary form of neuronal ceroid lipofuscinosis – a form of lysosomal storage disorder characterised by the accumulation of lipofuscin within the cells of the central nervous system." (PMID 34897416, 2021). "Finally, mutations in genes encoding the depalmitoylating enzyme PPT1 and the palmitoylated cysteine string protein (CSP; DNAJC5) cause neuronal ceroid lipofuscinosis a lysosomal-storage neurodegenerative disease." (PMID 34659801, 2021).
Parkinson disease (6 papers, 2017 to 2025). A progressive degenerative disorder of the central nervous system characterized by loss of dopamine producing neurons in the substantia nigra and the presence of Lewy bodies in the substantia nigra and locus coeruleus. "In addition to being associated with ANCL disease, the cysteine string proteins α (CSPα) encoded by the DNAJC5 gene have been implicated in several neurodegenerative diseases such as Alzheimer's disease (AD), Parkinson's disease (PD), and Huntington's disease." (PMID 36466613, 2022).
Kufs disease (5 papers, 2012 to 2025). "In any case, the molecular mechanisms by which the mutant versions of CSPα/DNAJC5 cause Kufs disease/CLN4 are not well understood yet." (PMID 40397740, 2025). "Mutations in DNAJC5/CLN4 cause an adult-onset form of NCL that is also known as Kufs disease or Parry disease." (PMID 27881166, 2016). "Kufs disease/CLN4 is an autosomal dominant neurodegenerative disorder caused by unknown mechanisms through Leu115Arg and Leu116Δ mutations in the DNAJC5 gene that encodes the synaptic vesicle co-chaperone cysteine string protein α (CSPα/DNAJC5)." (PMID 40397740, 2025). "Together, our results indicate that the absence of CSPα/DNAJC5 by itself does not cause the pathological lipofuscinosis that, on the other hand, is clearly observed in the transgenic mice expressing the mutant forms of CSPα/DNAJC5 causing Kufs disease/CLN4 in humans." (PMID 40397740, 2025). "Together, our data reveal that the transgenic expression of mutant forms of CSPα/DNAJC5 in neurons is enough to cause neuronal lipofuscinosis in mice that is similar to the pathological characteristics of Kufs disease/CLN4 in humans." (PMID 40397740, 2025). "Firstly, no reliable confirmation of Kufs disease in individuals with DNAJC5 mutations could be made by studying peripheral cells for lysosomal inclusions in the earlier stages of the disorder." (PMID 22235333, 2012). "We have found that transgenic mice expressing the mutations in DNAJC5 found in patients (L115R and L116Δ) develop neuronal lipofuscinosis with the pathological hallmarks observed in patients with Kufs disease/CLN4 and that this lipofuscinosis is not due to the lack of CSPα/DNAJC5." (PMID 40397740, 2025).
Parry disease (5 papers, 2016 to 2025). "Mutations in the CLN4 / DNAJC5 gene encoding CSPα underlie the adult onset form of NCL also called Parry disease, is a very rare and difficult to diagnose NCL." (PMID 30651094, 2019). "Parry disease, now classified as CLN4, is caused by mutations in the DnaJ heat shock protein family (Hsp40) Member C5 (DNAJC5) gene, which encodes cysteine‐string protein alpha (CSPα)." (PMID 39925015, 2025).
epilepsy (2 papers, 2020 to 2022). A brain disorder characterized by episodes of abnormally increased neuronal discharge resulting in transient episodes of sensory or motor neurological dysfunction, or psychic dysfunction. "Adult-onset neuronal ceroid lipofuscinosis (ANCL) is a rare neurodegenerative disease characterized by epilepsy, cognitive degeneration, and motor disorders caused by mutations in the DNAJC5 gene." (PMID 36466613, 2022). "DNAJC5, FRRS1L, SHANK3, SYN1, and SYN2 were epilepsy-related genes." (PMID 33584793, 2020).
Batten disease (1 paper, 2022). "Commonly known as Batten disease, the different subtypes are each caused by a mutation in a distinct ceroid lipofuscinosis neuronal (CLN) gene (PPT1/CLN1, TPP1/CLN2, CLN3, DNAJC5/CLN4, CLN5, CLN6, MFSD8/CLN7, CLN8, CTSD/CLN10, PGRN/CLN11, ATP13A2/CLN12, CTSF/CLN13)." (PMID 35252181, 2022).
liver cancer (1 paper, 2021). An epithelial or non-epithelial malignant neoplasm that arises from the liver. "Several homologs of the Hsp40/DnaJ protein family (DnaJB6, DnaJC1, DnaJC5, DnaJC7, and DnaJC21) have been identified as unfavorable prognostic markers in liver cancer." (PMID 34356495, 2021).
neuroblastoma (1 paper, 2023). Neuroblastoma (NB) is the most common solid, extracranial childhood tumor. "The secretion of endogenous α-syn mediated by DNAJC5 is also found in a human neuroblastoma cell line, SH-SY5Y, differentiated into neurons in the presence of retinoic acid, and in human-induced pluripotent stem cell-derived midbrain dopamine neurons." (PMID 36626307, 2023).
neurodegenerative disease (19 papers, 2012 to 2025). A disorder of the central nervous system characterized by gradual and progressive loss of neural tissue and neurologic function. "DNAJC5/CSP has been implicated in synaptic degeneration contributing to the pathogenesis of neurodegenerative diseases." (PMID 22952455, 2012). "Furthermore, recent studies have revealed that the neurodegenerative disease, adult onset neuronal ceroid lipofuscinosis, is caused by mutations in the human CSPα-encoding DNAJC5 gene." (PMID 25800794, 2015). "Mutations in the DNAJC5 gene that encodes CSPα cause autosomal dominant, adult-onset neuronal ceroid lipofuscinosis (ANCL), a rare neurodegenerative disease." (PMID 38193346, 2024). "DNAJC5 has been shown to control the release of neurodegenerative disease proteins but the mechanism of action of this protein in unconventional secretion remains elusive." (PMID 36626307, 2023). "The rare hereditary human neurodegenerative disease, autosomal-dominant adult-onset neuronal ceroid lipofuscinosis (ANCL), is caused by mutations in the DNAJC5 gene." (PMID 26419537, 2015). "By contrast, we found that DNAJC5/CSP levels are robustly and consistently increased in degenerating synapse-enriched fractions following injury and in synapse-enriched fractions from mouse models of neurodegenerative disease." (PMID 22952455, 2012). "DNAJC5, also known as cysteine string protein α (CSPα), is a co-chaperone of HSC70; it controls the extracellular release of many neurodegenerative disease proteins." (PMID 40552310, 2025). "This review focuses on one member, DnaJ Homolog Subfamily C Member 5 (DNAJC5), of the Hsp40/J-domain family of cochaperones and its role in linking the molecular mechanism of rare and common neurodegenerative diseases." (PMID 40621104, 2025). "DNAJC5, also known as cysteine string protein α (CSPα), is a co-chaperone of HSC70 and has been shown to control the extracellular release of many neurodegenerative disease proteins." (PMID 36626307, 2023).
infection (10 papers, 2017 to 2025). The state of being infected such as from the introduction of a foreign agent such as serum, vaccine, antigenic substance or organism. "Inhibitors of DNAJC5 (with a better efficiency than quercetin) or the MAPS pathway could be of considerable interest for adjunct therapy to treat infections with ExoU+ P. aeruginosa strains." (PMID 34188051, 2021). "Infection of A549 or DNAJC5−/− cells with ExoU-Bla-secreting bacteria produced similar ratios of blue/green fluorescence, indicating that the absence of DNAJC5 did not alter T3SS injection per se." (PMID 34188051, 2021).
tumor (6 papers, 2014 to 2025). "Specific to Europeans (MAF = 1.0e-04), loss of DNAJC5 exon 4 supported by 13 read-pairs and with around 50% reduction in read depth, was identified in a single European patient presenting for surgery at age 63 years with ISUP GG5 disease, yet appears to remain diploid during tumour development." (PMID 40064858, 2025). "All six amplifications that led to a substantial increase in expression in tumor samples were also reported as up-regulated HSP when comparing normal and tumor tissues (CCT3, HSPA6, DNAJA3, TRAP1, DNAJC5, and DNAJC5B)." (PMID 38816397, 2024).
autosomal dominant disease (1 paper, 2025). Autosomal dominant form of disease. "Because CLN4 is an autosomal-dominant disease, we considered to drive the expression of CLN4 CSPα/DNAJC5 mutant forms in neurons over a WT background as a potentially useful strategy to generate CLN4 animal models." (PMID 40397740, 2025).
movement disorder (1 paper, 2015). Neurological conditions resulting in abnormal voluntary or involuntary movement, which may impact the speed, fluency, quality and ease of movement. "Mutations in the human gene encoding CSP, DNAJC5, cause adult neuronal ceroid lipofucinosis (ANCL) which is characterised by progressive dementia, movement disorders, seizures and premature death." (PMID 26395859, 2015).
DNAJC5 also shares sentences with these, for which no sentence is quoted: malaria (7 papers); Adult onset (4); Alzheimer disease (3); cancer (2); glioblastoma (2); Intraventricular hemorrhage (2); prion disease (2); Ataxia (1); atherosclerosis (1); Autosomal dominant Kufs disease (1); autosomal recessive spastic ataxia (1); brain disease (1); breast tumor (1); cognitive deficits (1); dilated cardiomyopathy (1); Farber disease (1); generalized seizures (1); GM1 gangliosidosis (1); Lewy body diseases (1); lung carcinoma (1); lysosomal storage disorder (1); motor neuron disorder (1); multiple myeloma (1); Neurological disorders (1); osteosarcoma (1); parasites (1); Parkinsonism (1); Progressive myoclonic epilepsy (1); prostate carcinoma (1); retinitis pigmentosa (1).
A further 4 diseases each share a sentence with DNAJC5 in 1 paper.